RNU6-1303P (RNA, U6 small nuclear 1303, pseudogene)
Gene: Small nuclear RNA gene on chromosome 9 (77,635,203 to 77,635,309, reverse strand). Ensembl gene ENSG00000201711.
Homologues: Orthologues: chimpanzee U6 (97% identical), dog U6 (88% identical), rat LOC120101165 (85% identical), mouse Gm22359 (79% identical). Paralogues in human: RNU6-1060P (92% identical), RNU6-166P (91% identical), RNU6-41P (91% identical), RNU6-1024P (90% identical), RNU6-116P (90% identical), RNU6-15P (90% identical), RNU6-19P (90% identical), RNU6-48P (90% identical), RNU6-748P (90% identical), RNU6-949P (90% identical), RNU6-1011P (89% identical), RNU6-12P (89% identical), and 1288 more.